BRICD5 (BRICHOS domain containing 5)
Synonyms: C16orf79; MGC21830
Tractability: Antibody: UniProt predicts a signal peptide or a membrane-spanning region.
Gene: Protein-coding gene on chromosome 16 (2,209,253 to 2,210,905, reverse strand). Ensembl gene ENSG00000182685.
Subcellular location: Membrane
Subcellular location (Human Protein Atlas): Actin filaments; Nucleoplasm
Gene Ontology:
Molecular function: protein binding
Biological process: regulation of cell population proliferation
Cellular component: membrane
Genetic constraint (gnomAD): Loss-of-function variants: 51 observed, 27.27 expected, observed/expected ratio (o/e) 1.87, 90% interval 1.45 to 1.98. The synonymous counts are far from expectation, so gnomAD's model fits this gene poorly and the ratio says little. Missense variants: 456 observed, 302.34 expected, observed/expected ratio (o/e) 1.51, 90% interval 1.4 to 1.63. Synonymous variants: 177 observed, 121.2 expected, observed/expected ratio (o/e) 1.46, 90% interval 1.29 to 1.65.
Homologues: Orthologues: chimpanzee BRICD5 (98% identical), macaque BRICD5 (89% identical), dog BRICD5 (71% identical), pig BRICD5 (68% identical), rat Bricd5 (67% identical), mouse Bricd5 (66% identical), tropical clawed frog bricd5 (39% identical), zebrafish bricd5 (35% identical). Paralogues in human: GKN2 (14% identical), GKN1 (14% identical).
Diseases named in the same sentence as BRICD5 in open-access papers:
BRICD5 is named in the same sentence as 1 disease in open-access papers, as found by Europe PMC text mining. Sharing a sentence is not in itself a finding about the gene and the disease. The quoted sentences say what the papers report.
asthma (1 paper, 2023). "The elevated genes include those associated with cellular proliferation (BRICD5), those previously associated with asthma and other inflammatory diseases (IL1RL1, IL6R) and those involved in inflammatory cell signaling (LIME1) and function (SLC11A1)." (PMID 37876037, 2023). "Additionally, uPAR overexpression universally caused changes in the expression of genes related to cellular proliferation (BRICD5) and T‐cell/B‐cell signaling (LCK/LIME1) and importantly asthma via the IL33 receptor (IL1RL1), now a target for new asthma drugs." (PMID 37876037, 2023).